RNU6-550P (RNA, U6 small nuclear 550, pseudogene)
Gene: Small nuclear RNA gene on chromosome 4 (120,810,469 to 120,810,569, forward strand). Ensembl gene ENSG00000212359.
Homologues: Orthologues: chimpanzee U6 (97% identical), macaque U6 (95% identical), mouse Gm22583 (82% identical), mouse Gm24921 (80% identical). Paralogues in human: RNU6-128P (85% identical), RNU6-1145P (84% identical), RNU6-767P (84% identical), RNU6-1060P (83% identical), RNU6-116P (83% identical), RNU6-15P (83% identical), RNU6-188P (83% identical), RNU6-35P (83% identical), RNU6-47P (83% identical), RNU6-698P (83% identical), RNU6-738P (83% identical), RNU6-744P (83% identical), and 1286 more.